AVPR1A (arginine vasopressin receptor 1A)
Diseases named in the same sentence as AVPR1A in open-access papers (continued):
Sharing a sentence is not in itself a finding about the gene and the disease.
heart failure (6 papers, 2021 to 2025). Inability of the heart to pump blood at an adequate rate to meet tissue metabolic requirements. "Rats with CRF–CHF experienced exacerbated renal and cardiac failure, characterized by significant disturbances in water and sodium metabolism and abnormal expression of AVPR1a and AVPR2." (PMID 39588122, 2024). "Overactivation of AVPR1a may contribute to conditions such as hypertension, heart failure, and hyperfunction of the adrenal cortex." (PMID 39588122, 2024). "Due to the dual damage of heart failure and renal failure, CRF–CHF rats showed significant disturbances in sodium and water metabolism, and additionally, abnormal upregulation of AVPR1a and AVPR2 expression levels." (PMID 39588122, 2024).
Hypertension (5 papers, 2016 to 2024). The presence of chronic increased pressure in the systemic arterial system. "Single nucleotide polymorphisms (rs11174811 and rs3803107) in miR-375 target sites of the 3′-untranslated region in the arginine vasopressin receptor 1a gene were reported to be associated with the risk of hypertension." (PMID 35682548, 2022). "In the present study, we analyzed the correlation between rs11174811 and rs3803107 SNPs in the 3′ UTR of the AVPR1A gene and the risk of hypertension in the Chinese Han population." (PMID 31053625, 2019). "rs11174811 and rs3803107 SNPs in the AVPR1A gene are associated with the risk of hypertension in the Chinese Han population." (PMID 31053625, 2019). "The single nucleotide polymorphisms rs11174811 and rs3803107 in the AVPR1A gene are associated with an increased risk of hypertension in the Chinese Han population." (PMID 31053625, 2019). "Future studies are needed to identify how gene expression in response to early environmental exposures contributes to health outcomes, including how gene expression of AVPR1a contributes to cardiovascular outcomes, such as high blood pressure." (PMID 37888705, 2023). "We aimed to study the relationship between rs11174811 and rs3803107 single nucleotide polymorphisms (SNPs) in miRNA target sites of the 3′ UTR in the arginine vasopressin receptor 1a gene (AVPR1A) and the risk of hypertension in the Chinese Han population." (PMID 31053625, 2019). "In the present study, we analyzed the relationship between the SNPs, rs11174811, and rs3803107 in miRNA target sites within the AVPR1A 3′ UTR, and the risk of hypertension in the Chinese Han population." (PMID 31053625, 2019). "Four of them (Avpr1a, Hsd11b2, Agt, Ephx2) may provoke the hypertension development, and Mpo may contribute to insulin resistance and inflammation in the ISIAH rats." (PMID 28105924, 2016). "The discussion of ten of them known as associated with hypertension demonstrated that four of these genes (Avpr1a, Hsd11b2, Agt, Ephx2) may provoke the hypertension development, and Mpo may contribute to insulin resistance and inflammation in ISIAH rats." (PMID 28105924, 2016). "Therefore, we speculate that the regulation of AVPR1A expression by miR-526b, miR-375, and miR-186 may be related to the occurrence of hypertension." (PMID 31053625, 2019).
Obesity (5 papers, 2019 to 2025). Accumulation of substantial excess body fat. "Here, we used a mouse model to test the hypothesis that maternal high fat diet (mHFD)-induced obesity programs the risk for neurodevelopmental disorders by altering epigenetic regulation and transcription of Oxtr and Avpr1a in the offspring brain during late prenatal development." (PMID 30650536, 2019). "Quantitative PCR analysis indicated that mHFD-induced obesity resulted in male offspring-specific changes in Oxtr, but not Avpr1a expression, at GD 17.5." (PMID 30650536, 2019). "By contrast, mHFD-induced obesity did not alter hippocampal expression of Avpr1a in male or female offspring (Avpr1a: mHFD males 1.05 ± 0.08, control males 1.47 ± 0.32; mHFD females 1.01 ± 0.32, control females 1.097 ± 0.22)." (PMID 30650536, 2019).
prostate carcinoma (4 papers, 2019 to 2022). A carcinoma that arises from epithelial cells of the prostate gland. "Furthermore, both XDH (downregulated in liver tumors) and AVPR1A (upregulated in prostate cancer) have been implicated in the activity of cancer-related stem cells." (PMID 34206369, 2021). "Depletion of AVPR1A in castration-resistant prostate cancer cells resulted in decreased cell proliferation and reduced cyclin A." (PMID 34178625, 2021). "Also, many available datasets from human castrate-resistant prostate cancer specimens show that AVPR1A gene copy number amplification." (PMID 36326314, 2022). "Also, supports the use of again AVPR1A antagonists for advanced prostate cancer." (PMID 36326314, 2022). "They demonstrated that ectopic expression of AVPR1a is capable of conferring castration resistance and agonist treatment with the receptor ligand, the natural hormone arginine vasopressin, activates ERK and CREB, signaling molecules known to promote prostate cancer progression." (PMID 31998646, 2019).
breast carcinoma (3 papers, 2019 to 2024). "Moreover, the activation of c-JUN and AVPR1A target genes were associated with the invasive expressions of breast cancer cells, including enhanced tumor proliferation and angiogenesis." (PMID 37737712, 2023). "The results revealed a notable downregulation of AVPR1A, FEZ1, HGF, GSN, NEDD9, and EGR3 expression in the breast cancer cell lines (MCF7, BT-474, SK-BR-3, MDA-MB-231) when compared to the normal mammary epithelial cell line (MCF-10A)." (PMID 38756447, 2024). "In breast cancer cells expressing AVPR1a and AVPR2, natural vasopressin can activate both receptors but its affinity is higher for AVPR1a and the number of functional AVPR2 tends to be relatively low." (PMID 31998646, 2019). "On the contrary, when AVPR1a is blocked by selective antagonists such as relcovaptan or tumor cells are exposed to specific AVPR2 agonists such as desmopressin, significant antiproliferative effects are achievable in hormone-resistant breast cancer cell lines." (PMID 31998646, 2019).
hepatorenal syndrome (3 papers, 2024 to 2025). Hepatorenal syndrome is a form of impaired kidney function that occurs in individuals with advanced chronic liver disease. "As proof-of-concept, three genes encoding G protein-coupled receptors (SST3, SST5, and AVPR1A) that are current therapeutic targets in PH in the setting of acute variceal haemorrhage and hepatorenal syndrome were up-regulated." (PMID 38860875, 2024). "The AVPR1a agonist vasopressin (AVP), or terlipressin, is used in cases of postoperative bowel distention, refractory hypotension after cardiac surgery, intraoperative hypotension, or portal hypertension." (PMID 41375820, 2025).
schizophrenia (3 papers, 2016 to 2023). A major psychotic disorder characterized by abnormalities in the perception or expression of reality. "The aim of this study was to evaluate the expression of OXT, OXTR, AVP, and AVPR1a genes at the mRNA and protein levels in patients who have been suffering from schizophrenia for a long or short time." (PMID 35723404, 2022). "The aim of this study was to evaluate the expression of OXT, OXTR, AVP, and AVPR1a genes at the mRNA and protein levels in patients with schizophrenia." (PMID 35723404, 2022). "The statistical analyses comparing the expression values of OXT, OXTR, AVP, and AVPR1a genes in the investigated groups allow us to conclude that all the examined genes may participate in the etiopathogenesis of schizophrenia." (PMID 35723404, 2022). "Moreover, the expression of OXT, OXTR, and AVPR1a genes both at the mRNA and protein levels differed statistically significantly in the group of individuals that were suffering from schizophrenia for a long and short period." (PMID 35723404, 2022). "OXT, OXTR, AVP, and AVPR1a are genes that may be involved in the development of schizophrenia." (PMID 35723404, 2022). "OXT and AVPR1a gene expression was significantly lower in the schizophrenia group than in the controls, whereas OXTR and AVP gene was significantly higher in the schizophrenia subjects than in the controls." (PMID 35723404, 2022). "OXT and AVPR1a gene expression at both the mRNA and protein levels were significantly lower in the schizophrenia group, and OXTR and AVP gene expression at both the mRNA and protein levels was higher in the schizophrenia subjects than in the controls." (PMID 35723404, 2022).
chronic kidney disease (2 papers, 2024 to 2025). Impairment of the renal function secondary to chronic kidney damage persisting for three or more months. "This study was to investigate the abnormalities in water and sodium metabolism, as well as the expression levels of arginine vasopressin receptor 1a (AVPR1a) and arginine vasopressin receptor 2 (AVPR2), in a rat model of chronic renal failure–chronic heart failure (CRF–CHF)." (PMID 39588122, 2024).
lung cancer (2 papers, 2003 to 2022). A malignant neoplasm involving the lung. "AVPR1A is expressed on various cell lines such as vascular smooth muscle, cardiomyocytes, hippocampus, kidney, bone, liver, and breast and nonsmall cell lung cancer." (PMID 36326314, 2022).
thyroid cancer (2 papers, 2020 to 2022). "Among the top 30 hub genes obtained in PPI network, the expression levels of FN1, NMU, CHRDL1, GNAI1, ITGA2, GNA14 and AVPR1A were associated with the prognosis of thyroid cancer." (PMID 32337286, 2020). "According to our analysis, we predicted that AVPR1A might also be associated with the development of thyroid cancer, but experimental data were needed to confirm this specific link." (PMID 32337286, 2020). "Interestingly, the arginine vasopressin receptor, AVPR1A, was also found to be downregulated in thyroid cancer and associated with progression-free survival, while it was upregulated in castration-resistant prostate cancer with an antitumoral effect of a selective AVPR1A antagonist." (PMID 35203352, 2022). "Using data mining based on bioinformatics tools, the present study has confirmed CHRDL1, GNAI1, GNA14 and AVPR1A are associated with thyroid cancer although their specific biological functions have not been explored by the molecular biology methods." (PMID 32337286, 2020). "Hence, we derived seven key genes related to the prognosis of thyroid cancer: FN1, NMU, CHRDL1, GNAI1, ITGA2, GNA14, AVPR1A." (PMID 32337286, 2020). "Nor did we find evidence of the link between AVPR1A and thyroid cancer." (PMID 32337286, 2020).
adenoma (1 paper, 2013). A neoplasm arising from the epithelium. "Expression of mRNA of vasopressin receptors (AVPR1A, AVPR2, AVPR1B) was studied in a panel of adrenocortical tissues, consisting of AIMAH, normal adrenals, ACTH-dependent hyperplasias, adenomas and carcinomas." (PMID 24034279, 2013).
fatty liver (1 paper, 2022). "Plasma vasopressin (VP) is increased in diabetic patients and promotes fatty liver by activating hepatic arginine VP receptor 1A (Avpr1a)." (PMID 35614477, 2022).
gastroenteritis (1 paper, 2024). An inflammatory disorder that affects the upper and lower gastrointestinal tract. "Relevant to our findings, Avpr1a may represent a novel point of convergence between VH following transient gastroenteritis and stress-induced VH that could explain the stress-induced pain exacerbations that many DGBI patients experience." (PMID 38768798, 2024).
glycogenosis (1 paper, 2024). "AVPR1A encodes a receptor that mediates cell contraction and proliferation, platelet aggregation, and glycogenosis, and its expression was associated with drug use disorders." (PMID 38992651, 2024).
leiomyoma (1 paper, 2023). A well-circumscribed benign smooth muscle neoplasm characterized by the presence of spindle cells with cigar-shaped nuclei, interlacing fascicles, and a whorled pattern. "ST images showed that OXTR and AVPR1A were highly expressed in pseudocapsule area instead of leiomyoma area." (PMID 37215998, 2023). "Besides AVPR1A and OXTR, we further found PTGER3, one of top DEGs, was highly expressed on the smooth muscle cells in pseudocapsule compared to leiomyoma, indicated that PGE2 might be another candidate." (PMID 37215998, 2023).
mood disorder (1 paper, 2025). A cognitive disorder a disturbance in which the person's mood is hypothesized to be the main underlying feature. "Furthermore, blocking AVPR1a in the ventral hippocampus has been found to alleviate mood disorder behaviors in rats." (PMID 40437391, 2025).
myocardial infarction (1 paper, 2019). Gross necrosis of the myocardium, as a result of interruption of the blood supply to the area, as in coronary thrombosis. "Studies have found that the rs11174811 SNP in an miRNA binding site within the AVPR1A gene, and is correlated with elevated blood pressure and risk of myocardial infarction in Caucasians." (PMID 31053625, 2019).
paraganglioma (1 paper, 2022). A benign or malignant neoplasm arising from paraganglia located along the sympathetic or parasympathetic nerves. "Among the seven down-regulated GPCRs in paraganglioma, Arginine Vasopressin Receptor 1A (AVPR1A), ACTH receptor, MC2R, and PTH1R were the target of 2 to 4 drugs each." (PMID 35203352, 2022).
psychosis (1 paper, 2023). "On the other hand, we also reported increased expression of AVP and AVPR1A in the placentas of women who underwent a first-episode psychosis during pregnancy." (PMID 37373400, 2023).
steatosis (1 paper, 2024). Increased lipid within the cytoplasm of cells. "Genes involved in steatosis (Cd36, Lpl), hepatoxicity (Avpr1a, Pla2g12a), necrosis (Serpine1), fatty acid metabolism (Acox1, Cpt1b, Cyp4a10, Ehhadh), lipid transport (Apoa1), and PPAR transcription factors (Pparδ) were altered with PFHpS exposure compared to vehicle-exposed animals." (PMID 39066581, 2024).
uroepithelial carcinomas (1 paper, 2023). "The identification of c-KIT and AVPR1A as two differentially expressed genes with known effects on promotion of cell growth and mTORC1 activation in uroepithelial carcinomas and other malignancies is likely a first step toward the exciting discovery of new therapies for this devastating disease." (PMID 38028758, 2023).
tumor (5 papers, 2022 to 2025). "Specifically, both SLC5A5 and AVPR1A were downregulated in tumor and LNM tissues." (PMID 38974575, 2024). "Furthermore, in vivo treatment with an AVPR1A antagonist (Relcovaptan) resulted effective in the control of orthotopic and subcutaneous xenograft tumors growth after mice castration, suggesting that the stimulation of this receptor promotes tumor growth in castration resistant PCa." (PMID 39910005, 2025).
cancer (4 papers, 2013 to 2024). A tumor composed of atypical neoplastic, often pleomorphic cells that invade other tissues. "But evidence on the association between AVPR1A and cancer is rare." (PMID 32337286, 2020). "The AVPR1A gene with decreased expression in the HG-ESS differed in 15 cancer types." (PMID 38167455, 2024). "Expression was evaluated across 34 cancers, identifying immune DEGs IGF1 and AVPR1A." (PMID 38167455, 2024).
psychiatric disorder (4 papers, 2013 to 2023). A disorder characterized by behavioral and/or psychological abnormalities, often accompanied by physical symptoms. "We then examined methylation in a shortlist of genes that were previously associated with early life stress and psychiatric disorders as well as placental functioning: Ank3, Avp, Avpr1a, Avpr1b, Bdnf, Cacna1c, Cyp11b1, Cyp11b2, Fkbp5, Hsd11b1, Igf2, Morc1, Nr3c1, Oxt, Oxtr, Pclo, Slc6a4." (PMID 30655507, 2019).
neurodevelopmental disorder (3 papers, 2016 to 2026). A behavioral and cognitive disorder with onset during the developmental period that involves impaired or aberrant development of intellectual, motor, or social functions. "Thus, further understanding of how stress in early life influences Avpr1a gene expression in the brain could lead to novel intervention strategies for neurodevelopmental disorders associated with dysfunctional social behaviours." (PMID 26613552, 2016). "These neuropeptides signal via their cognate G protein-coupled receptors, arginine vasopressin 1A (Avpr1a) and oxytocin receptor (Oxtr), to modulate diverse aspects of human social behavior, and dysfunction of these systems are well established in neurodevelopmental disorders." (PMID 30650536, 2019). "Our data support a role for altered signalling via central Avpr1a in PNS‐induced sex‐dependent changes in social memory and may have implications for understanding the aetiology of neurodevelopmental disorders characterised by social behaviour deficits in humans." (PMID 26613552, 2016).
immune dysfunction (1 paper, 2021). "However, mRNA expression of Oxtr and Avpr1a in the PVN were not affected in the C-section model suggesting that this may not be the mechanism of immune dysfunction at play here." (PMID 34040156, 2021).
AVPR1A also shares sentences with these, for which no sentence is quoted: cardiac hypertrophy (3 papers); Hyperglycemia (3); Insulin resistance (3); Sepsis (3); diabetes (2); Impaired glucose tolerance (2); metabolic disease (2); metabolic syndrome (2); septic shock (2); Stroke (2); adenocarcinoma (1); Alzheimer disease (1); Andersen-Tawil syndrome (1); anxiety disorder (1); chronic heart failure (1); cognitive deficits (1); colitis (1); colon carcinoma (1); colon diseases (1); colorectal cancer (1); endocrine diseases (1); endometrial cancer (1); endotoxemia (1); Follicular Cyst (1); glomerulosclerosis (1); Huntington disease (1); hypercortisolism (1); Hyponatremia (1); inflammatory bowel disease (1); itch (1).
A further 15 diseases each share a sentence with AVPR1A in 1 paper.